YTHDF1 (YTH N6-methyladenosine RNA binding protein F1)
Diseases named in the same sentence as YTHDF1 in open-access papers (continued):
Sharing a sentence is not in itself a finding about the gene and the disease.
cancer (continued). "In cervical cancer (CC) cells, YTHDF1 accelerates m6A-augmented glycolysis and cancer progression by promoting translational elongation of pyruvate dehydrogenase kinase 4 (PDK4) mRNA and stabilization of hexokinase 2 (HK2) mRNA." (PMID 36999016, 2023). "Numerous studies demonstrated that YTHDF1 exerted an important role in tumorigenesis and metastasis of cancers by different mechanisms, such as promoting translation or regulating the stability of mRNAs." (PMID 36707507, 2023). "After that, PDK4 and IGF2BP3 combine to obtain stronger stability, or combine with YTHDF1/eEF-2 complex to improve translation efficiency and ultimately promote glycolysis and proliferation of cancer cells." (PMID 37582735, 2023). "The amplification of the YTHDF1 DNA copy number is a common event in cancer, leading to the overexpression of YTHDF1 in this disease." (PMID 38202722, 2023). "Collectively, targeting YTHDF1 represents a promising approach for the future management of human cancers." (PMID 36650570, 2023). "Genetic depletion of YTHDF1 sensitizes human tumors to chemotherapy and immunotherapy, suggesting that YTHDF1 antagonists can be potential adjuvants in cancer therapy." (PMID 36650570, 2023). "We analyzed the amplification of YTHDF1 in 10712 samples from 32 studies with various cancers in cBioPortal database." (PMID 36707507, 2023). "YTHDF1 binds the m6A-modified mRNA of c-Myc, whose enhanced translation promotes glycolysis and cancer cell proliferation." (PMID 37086786, 2023). "We propose that YTHDF1 is a promising future cancer biomarker for detection, progression, and prognosis." (PMID 36650570, 2023). "We found that KLF3 expression was generally positively correlated with m1A, m5C, and m6A-related gene expression in pan-cancer, especially in YTHDF1, NSUN3, TET2, METTL14, YTHDC2, and FMR1." (PMID 37600783, 2023). "Here, we reviewed the potential targeted proteins and regulatory mechanism of YTHDF1 in the tumorigenesis and metastasis of various human cancers." (PMID 36707507, 2023). "Wang utilized an FDA-approved LNP formulation to design LNP-siRNA drugs targeting YTHDF1, directly silencing its expression and thereby achieving the inhibition of cancer progression." (PMID 38202722, 2023). "In terms of clinical application, YTHDF1 was reported to be an independent marker for the diagnosis and prognosis of human cancer." (PMID 36650570, 2023). "More and more evidence supports that YTHDF1 acts as an oncogene by affecting signaling pathways in cancers, including HCC, breast cancer, NSCLC, CRC, and Merkel cell carcinoma." (PMID 37437245, 2023). "In summary, most of the studies reported thus far indicate that YTHDF1 is highly expressed in human cancers and correlates with poor prognosis, implying that YTHDF1 functions as an oncogenic factor." (PMID 36650570, 2023). "Understanding the expression patterns of YTHDF1 in various types of cancer is of great significance for clinical diagnosis and guidance." (PMID 38202722, 2023). "Here, we have found the expression of CCND1 was obviously decreased in METTL3-deleted cells, and the same result was also demonstrated in YTHDF1-silenced cancer cells." (PMID 38001065, 2023). "YTHDF1 can also trigger translational elongation through interaction with elongation factors in some cancer cells." (PMID 36999016, 2023). "This remarkable medication has the ability to directly disrupt the binding between YTHDF1 and m6A-mRNA, thus inhibiting YTHDF1’s translation of cyclin E2 and subsequently slowing down cancer progression." (PMID 38202722, 2023). "Very solid evidence supports the pivotal role of YTHDF1 in embryonic development and human cancer progression." (PMID 36650570, 2023). "Overwhelming evidence substantiates that dysregulation of YTHDF1 is tightly correlated with the malignant progression of various cancer." (PMID 36650570, 2023). "Due to the significant role of YTHDF1 in cancer, targeted therapies directly aimed at YTHDF1 have been proposed." (PMID 38202722, 2023).
cancer (continued). "YTHDF1 plays an essential role in different kinds of cancers and can increase the translation efficiency of m6A-modified mRNA in a cap-independent manner." (PMID 37259333, 2023). "High expression of YTHDF1 and METTL3 has been reported to be associated with lower OS in cancer patients, and YTHDF2, YTHDF1 and METTL3 were proved to be associated with sorafenib treatment and anti-PD-1 immunotherapy response in HCC." (PMID 36618420, 2022). "Previous studies have indicated that YTHDF1 plays an important bio-function in human malignant tumors." (PMID 35156522, 2022). "Studies have shown that YTHDF1 plays an important role in the process of post-transcriptional modification by regulating the expression of genes involved in cancer, cell proliferation, cell migration and invasion, inflammation, immunity, and autophagy." (PMID 35884552, 2022). "Even if the specific effect of YTHDF paralogue proteins is currently under debate, many studies reported the importance of YTHDF1 in the regulation of translation in cancer." (PMID 36012237, 2022). "For instance, hypoxia in breast cancer induces HIF-1α expression and promotes the effect of PKM2 on glycolysis through upregulation of YTHDF1, triggering cancer cell growth and metastasis." (PMID 35794625, 2022). "Among them, YTHDF1 is the most versatile and powerful m6A reader protein and is involved in the regulation of diverse cancers." (PMID 36551532, 2022). "Previous studies showed that upregulated expression of readers such as YTHDF1 promotes the progression of some cancers, such as NSCLC and ovarian cancer." (PMID 35296338, 2022). "In vitro and in vivo experimental evidence largely supports the role of YTDHF1 in promoting cancer initiation, progression, and metastasis, which suggests the oncogenic function of YTHDF1 in GI cancers." (PMID 35884552, 2022). "Lower m6A levels in myeloid cells enhance cancer progression by blocking the YTHDF1-mediated translation of SPRED2, and knockout of METTL3 induced a higher count of M2 macrophages in the TME69." (PMID 35794212, 2022). "In the first case, the m6A deposition in keratin 7 (KRT7), an important mediator of cancer metastases, stimulates its translation via the YTHDF1/eEF1 axis." (PMID 36012237, 2022). "Mechanistically, YTHDF1 regulates the expression of target genes by promoting translation, thereby participating in cancer-related signaling pathways." (PMID 35884552, 2022). "We found that YTHDF1 was significantly correlated with immune cell infiltration in 18 cancers, involving 15 immune cell types, among which macrophages were correlated with 11 cancers and mast cell resting were correlated with five cancers." (PMID 35075167, 2022). "Growing evidence has demonstrated the critical roles of YTHDF1 and its molecular mechanism in different cancers." (PMID 35884552, 2022). "Taken together, our findings provided new light into the critical role of YTHDF1 in OS development, and indicated the novel significance of the molecular mechanism of m6A epi-transcriptomic modification in cancer research." (PMID 35156522, 2022). "Considering the redundant functions of YTHDF1–3, we evaluated the role of YTHDF proteins across cancer types by calculating the R1 signature based on the expression of YTHDF1–3." (PMID 35794212, 2022). "YTHDF1 is also a novel therapeutic target for cancer immunotherapy (WO2020132536 (A1), from the CDDI database)." (PMID 36226062, 2022). "And methylation of CDS of Snail, which recruited the YTHDF1 and eEF‐2, can trigger its translation elongation and cancer metastasis." (PMID 35678231, 2022). "It is believed that YTHDF1 promotes mRNA translation by recognizing m6A sites to regulate cancer progression." (PMID 36551532, 2022). "YTH domain-containing family protein 1 (YTHDF1) or YTHDF2 play crucial roles in cancer immunotherapy." (PMID 36479088, 2022).
cancer (continued). "To further elucidate the cancer promoting role of YTHDF1 in vivo, we injected MKN74 cells expressing control vector, shYTHDF1-1 or shYTHDF1-2 into the right dorsal flank of NSG mice." (PMID 35193930, 2022). "The cancer inhibitory effect of miR-16-5p and rescuing effect of YTHDF1-expressing plasmids were also consistently supported by EDU staining, which showed similar trends to the results of the CCK analysis." (PMID 35319018, 2022). "We then performed CCK-8 and EdU cell proliferation assays using scramble shRNA transduced MDA-MB-231 and MCF-7 cells (sh-NC) and sh-YTHDF1 transduced cancer cells." (PMID 35197112, 2022). "Hypoxia, c-Myc, the Wnt/β-catenin signaling pathway, the m6A “eraser” ALKBH5, and miR-3436 were reported to regulate YTHDF1 expression in cancer research." (PMID 36550542, 2022). "YTHDF1 was reported to be involved in regulating cancer cell growth, metastasis, and drug resistance via controlling the mRNA stability of cancer related genes." (PMID 36291811, 2022). "Knockdown of YTHDF1 suppressed cancer stem cell-like characteristics in OC cells resistant to cisplatin." (PMID 36545327, 2022). "TCGA cohort analysis demonstrated that YTHDF1 was highly expressed in 17 cancers and was low in 2 cancers." (PMID 35401696, 2022). "Recent studies have demonstrated that YTHDF1 plays a crucial role in cancer development and durable neoantigen-specific antitumor immunity." (PMID 34026603, 2021). "Since our RT-qPCR results verified the expression of ALKBH5 and YTHDF1 in 12 pairs of cancer and normal tissues, we inferred Cluster 1 to represent the overall immunological characteristics of COAD, thus showing poor immune response." (PMID 34079761, 2021). "YTHDF1, as a pivotal “reader” protein in m6A regulators, plays important role in different kinds of cancers." (PMID 34088349, 2021). "In the first step of our study, we used the Oncomine, TIMER, GEPIA, and BioGPS databases to determine the expression level of YTHDF1 in cancers and normal tissues." (PMID 34026603, 2021). "Subsequently, we explored the associations between YTHDF1 expression and ICP genes in human cancers to explore the potential of YTHDF1 in immunotherapy." (PMID 34026603, 2021). "YTHDF1, a reader of m6A, can promote the translation of some transcripts to change the proteome in cancer cells, therefore regulating tumorigenesis." (PMID 33795663, 2021). "Deletion YTHDF1 in vitro impeded cancer cell proliferation and inhibited cancer progression in vivo." (PMID 34745970, 2021). "YTHDF1 not only participates in mRNA translation, which directly targets YTHDF1 or binds to translational initiation factors in some cancer cells but is also involved in neoantigen-specific immunity." (PMID 34630412, 2021). "YTHDF1 is an m6A “reader” widely distributed in the body, including the bone marrow, and plays important roles in cancer progression, neuronal development, and regeneration, as well as stem cell proliferation, differentiation, and aging." (PMID 34772913, 2021). "The expression of YTHDF1 in different cancer cell lines and normal tissues was investigated via the BioGPS database, and we found that YTHDF1 had a high expression level in almost all cancer cell lines." (PMID 34026603, 2021). "Silencing YTHDF1 rendered cancer cells resistant to cisplatin treatment, which showed a bad clinical outcome." (PMID 34745970, 2021). "In this study, the role of YTHDF1 in prognosis and immunology in human cancers was comprehensively analyzed." (PMID 34026603, 2021). "As a result, implementing small molecules or DC vaccines that can suppress YTHDF1 would enhance immunotherapy against cancers." (PMID 34526985, 2021). "YTHDF1 targeting can be a viable option for cancer therapy, as its elevation promotes cancer growth in different cancers, including GC, ovarian cancer, CRC, and HCC." (PMID 34526985, 2021). "YTHDF1 plays an essential role in a variety of cancers as a core factor of RNA methylation modification." (PMID 34677810, 2021).
cancer (continued). "We comprehensively analyzed the expression of YTHDF1 in pan-cancer and corresponding normal tissues." (PMID 34434939, 2021). "The other three YTH family proteins, YTHDF3, YTHDC1, and YTHDC2, were found to be less correlated with human cancer than YTHDF1 and YTHDF2." (PMID 33795663, 2021). "This is particularly significant in the field of cancer research, for example, YTHDF1 can play both a cancer-promoting and a cancer suppressing role in different cancers." (PMID 34103054, 2021). "This study aimed to explore the potential of YTHDF1 in anticancer immunotherapy in human cancer, thus offering insight to a new antitumor strategy." (PMID 34026603, 2021). "The TISIDB database was used to determine YTHDF1 expression in different immune and molecular subtypes of human cancers." (PMID 34026603, 2021). "Next, the role of YTHDF1 expression on immune and molecular subtypes among human cancers was explored with the TISIDB website." (PMID 34026603, 2021). "Of note, HIF-1α-mediated upregulation of YTHDF1 under hypoxia in HCC cells provides evidence that adaptation of cancer epigenetics to hypoxic stress forces HCC malignancy, at least in part, for the translation of m6A-containing oncogene mRNAs." (PMID 33619246, 2021). "In patientswith high-risk cancer, ZC3H13 expression is upregulated, while the expression of METTL3, KIAA1429, YTHDF1 and YTHDF2 is downregulated." (PMID 34246319, 2021). "We analyzed the RNA expression level of YTHDF1 using the Cancer Cell Line Encyclopedia4 database, in which AGS had the highest expression of YTHDF1 among GC cell lines." (PMID 33791305, 2021). "As the role of YTHDF1 in m6A modification has been revealed, more studies have described the effects of YTHDF1 on disease progression, especially cancer." (PMID 34088349, 2021). "Then, we explored YTHDF1 expression in different immune subtypes and molecular subtypes of human cancers to determine its potential mechanism of action." (PMID 34026603, 2021). "In the future, a prospective study of YTHDF1 expression and its role in human cancers’ immune infiltration is needed, along with successful development and testing of a new antitumor immunotherapy drug targeting YTHDF1." (PMID 34026603, 2021). "Consistently, our recent study indicated that methylation of CDS of Snail, which recruited the YTHDF1 and eEF-2, can trigger its translation elongation and cancer metastasis." (PMID 32444598, 2020). "The data strongly suggest that YTHDF1 plays a pivotal role in cancer progression by regulating intracellular iron metabolisms." (PMID 33204330, 2020). "Consistently with our results, YTHDF1 ablation has previously been shown to result in decreased proliferation in different types of cancer, including colorectal and lung carcinomas." (PMID 33317545, 2020). "YTHDF1 expression is amplified in various types of cancers, including HNSCC; furthermore, it has a critical oncogenic role 31-38." (PMID 33204330, 2020). "ZC3H13 was upregulated in patients with high cancer risk, whereas METTL3, KIAA1429, YTHDF1, and YTHDF2 were downregulated." (PMID 32631107, 2020). "In vitro and in vivo experiments indicated that downregulating YTHDF1 suppressed cancer growth, colony formation, and immigration and reduced intracellular iron content, Fe2+ and ROS levels in HPSCC cells." (PMID 33204330, 2020). "Next, we also analyzed the expression of YTHDF1 in different types of cancer by analyzing the Ramaswamy multi-cancer dataset from the Oncomine database." (PMID 33317545, 2020).
cancer (continued). "Silencing of YTHDF1 significantly downregulated the expression of cancer stem cell markers but notably upregulated the enterocyte markers expression, suggesting that YTHDF1 was involved in modulating the stem cell-like activity in CRC." (PMID 32276589, 2020). "The results showed that YTHDF1 silencing significantly downregulated the expression of CRC cancer stem cell markers." (PMID 31131257, 2019). "We found that YTHDF1 is highly expressed in BC and high grade, suggesting a potential carcinogenic effect of YTHDF1 in cancer." (PMID 31808521, 2019). "Here, the authors show that a gene involved in hypoxia, YTHDF1, underwent rapid evolution in Tibetans and their domestic animals, and find that the gene is amplified in some cancers and contributes to drug resistance in hypoxic conditions." (PMID 31653849, 2019). "YTHDF1 expression is decreased in highland mammals compared to lowlanders, furthermore it is amplified in various types of cancers including NSCLC." (PMID 31653849, 2019). "Taken together with the present observation of YTHDF1 role in cancer cell proliferation, the data suggest the candidacy of YTHDF1 as a possible therapeutic target." (PMID 29484125, 2018). "Although downstream targets of YTHDF1 need to be elucidated in future studies, our findings clearly indicated that epigenetic regulation by YTHDF1 plays an important role in cancer progression processes in CRC." (PMID 29484125, 2018). "We then studied the functional role of Ythdf1 in cancer cell growth and chemoresistance as well as the transcriptional control of YTHDF1 transcript." (PMID 29484125, 2018). "The in vitro study showed that the knockdown of YTHDF1 resulted in the suppression of cancer proliferation and sensitization to the exposure of anticancer drugs such as fluorouracil and oxaliplatin." (PMID 29484125, 2018). "Remarkably, our above evidence supports a notion that EZH2 may further facilitate oncogenesis via enhancing the translation of a series of cancer regulators through its catalytic activity, with YTHDF1 playing a pivotal role in this process." (PMID 41252201, 2026). "We also detected the amplification or gain of the YTHDF1 gene in a substantial proportion of samples from The Cancer Genome Atlas (TCGA) GC cohort (n = 410, 65.0%) and the Cancer Cell Line Encyclopedia (CCLE; all cell lines, n = 916, 14.2%; GC cell lines, n = 47, 14.9%)." (PMID 39587835, 2025). "YTHDF1 has been identified as an oncogenic factor in various types of cancer." (PMID 40675967, 2025). "Given the crucial role of Notch signaling in maintaining cancer stemness, we investigated whether YTHDF1-induced NOTCH1 translation drives stemness in colorectal CSCs." (PMID 41423446, 2025). "Similarly, YTHDF1 has demonstrated prognostic significance in the cancer tissues of patients with CRC." (PMID 39987091, 2025). "YTH domain family 1 (YTHDF1), an m6A “reader”, is expressed at elevated levels in various cancers." (PMID 40278596, 2025). "However, the study failed to establish a direct m6A-dependent regulatory association between YTHDF1 and c-MYC, thereby leaving room for investigating the divergent regulatory effects of YTHDF1 on c-MYC across different cancers." (PMID 41167308, 2025). "Notably, the m6A reader protein YTHDF1 is generally overexpressed in various cancer tissues, including lung cancer and GC." (PMID 41446042, 2025). "YTHDF1 is closely related to the poor clinical prognosis of diverse malignant tumors." (PMID 41167308, 2025). "Our work also indicates that targeting YTHDF1 might be a viable strategy for blocking aberrant NOTCH signaling in cancer." (PMID 41423446, 2025). "In addition to the dysregulation of genes and proteins related to cancer immunity, YTHDF1 overexpression led to the enhanced synthesis of proteins associated with cell cycle progression and DNA synthesis, as revealed by proteomic analysis." (PMID 39587835, 2025). "YTHDF1 has a regulatory role as a cancer‐promoting factor in the development of GC." (PMID 38444279, 2024).